VAPA (VAMP associated protein A)
Description:
Endoplasmic reticulum (ER)-anchored protein that mediates the formation of contact sites between the ER and endosomes via interaction with FFAT motif-containing proteins such as STARD3 or WDR44. STARD3-VAPA interaction enables cholesterol transfer from the ER to endosomes. Via interaction with WDR44 participates in neosynthesized protein export. In addition, recruited to the plasma membrane through OSBPL3 binding. The OSBPL3-VAPA complex stimulates RRAS signaling which in turn attenuates integrin beta-1 (ITGB1) activation at the cell surface. With OSBPL3, may regulate ER morphology. May play a role in vesicle trafficking.
Synonyms: VAMP-A; VAP-A; VAP-33; VAP33; hVAP-33
Tractability: Antibody: UniProt places it where antibodies can reach, with high confidence; its Gene Ontology location is reachable by antibodies, with high confidence; UniProt predicts a signal peptide or a membrane-spanning region. PROTAC: ubiquitination databases record sites on it; its protein half-life has been measured.
Gene: Protein-coding gene on chromosome 18 (9,913,916 to 9,960,021, forward strand). Ensembl gene ENSG00000101558.
Subcellular location: Endoplasmic reticulum membrane; Cell membrane; Cell junction, tight junction; Nucleus membrane
Subcellular location (Human Protein Atlas): Endoplasmic reticulum
Pathways (Reactome):
Immune System: Neutrophil degranulation
Metabolism: Sphingolipid de novo biosynthesis
Protein localization: Insertion of tail-anchored proteins into the endoplasmic reticulum membrane
Gene Ontology:
Molecular function: cadherin binding; endoplasmic reticulum-endosome tether activity; FFAT motif binding; microtubule binding; protein binding; protein domain specific binding; protein heterodimerization activity; protein homodimerization activity; protein-membrane adaptor activity
Biological process: ceramide transport; cholesterol homeostasis; cholesterol transport; COPII-coated vesicle budding; endoplasmic reticulum organization; endoplasmic reticulum to Golgi vesicle-mediated transport; host-mediated activation of viral genome replication; host-mediated suppression of viral genome replication; neuron projection development; phospholipid transport; positive regulation of canonical NF-kappaB signal transduction; protein folding in endoplasmic reticulum; protein localization to endoplasmic reticulum; regulation of focal adhesion assembly; sphingomyelin biosynthetic process; sterol transport; viral release from host cell; membrane fusion
Cellular component: bicellular tight junction; endoplasmic reticulum; endoplasmic reticulum exit site; endoplasmic reticulum membrane; Golgi membrane; perinuclear region of cytoplasm; plasma membrane; vesicle; azurophil granule membrane; cytosol; nuclear membrane; microtubule cytoskeleton
Genetic constraint (gnomAD): Loss-of-function variants: 3 observed, 19.25 expected, observed/expected ratio (o/e) 0.16, 90% interval 0.07 to 0.4. The upper end of that interval is the gene's LOEUF score, 0.4, which puts it in group 1 of 6, group 1 being the genes least tolerant of losing a copy. Missense variants: 202 observed, 224.22 expected, observed/expected ratio (o/e) 0.9, 90% interval 0.8 to 1.01. Synonymous variants: 87 observed, 81.13 expected, observed/expected ratio (o/e) 1.07, 90% interval 0.9 to 1.28.
Homologues: Orthologues: chimpanzee VAPA (99% identical), macaque VAPA (99% identical), dog VAPA (98% identical), mouse Vapa (97% identical), rat Vapa (97% identical), rabbit VAPA (92% identical), pig VAPA (90% identical), guinea pig VAPA (87% identical), zebrafish vapal (72% identical), tropical clawed frog vapa (71% identical), rat Mospd4 (54% identical), Drosophila melanogaster Vap33 (38% identical), and 7 more. Paralogues in human: VAPB (61% identical).
Diseases named in the same sentence as VAPA in open-access papers:
VAPA is named in the same sentence as 38 diseases in open-access papers, as found by Europe PMC text mining. Sharing a sentence is not in itself a finding about the gene and the disease. The quoted sentences say what the papers report.
pneumonia (4 papers, 2016 to 2024). An acute, acute and chronic, or chronic inflammation focally or diffusely affecting the lung parenchyma, caused by an infection in one or both of the lungs (by bacteria, viruses, fungi, or mycoplasma.). "The virulence-associated protein A (VapA) produced by virulent Rhodococcus equi allows it to replicate in macrophages and cause pneumonia in foals." (PMID 38018994, 2024). "Odds ratios for the outcome of pneumonia associated with VapA activity-level and farm." (PMID 34437551, 2021). "Indeed, most R. equi strains that cause pneumonia in foals and many strains that cause pneumonia in humans carry the plasmidic vapA+ gene." (PMID 31817114, 2019). "It has long been acknowledged that clinical isolates of the facultative intracellular bacterium R. equi obtained from foals with pneumonia and associated disease manifestations carry an ~80-kb virulence plasmid (pVAPA1037) and express the crucial virulence determinant VapA." (PMID 27747295, 2016). "Among RE HIP-transfused foals, the odds of pneumonia were approximately 6-fold higher (P = 0.0005) among foals with VapA antibody activity ≤ the population median." (PMID 34437551, 2021). "The association of a higher activity of antibodies against either VapA or PNAG with reduced odds of pneumonia was observed even after accounting for effects of farm, indicating that transfusion of either plasma protected against both clinical and subclinical pneumonia." (PMID 34437551, 2021). "Antibody activities against PNAG and the rhodococcal virulence-associated protein A (VapA), and to deposition of complement component 1q (C՛1q) onto PNAG were determined by ELISA, and then associated with either clinical pneumonia at Farm A (n = 119) or subclinical pneumonia at Farm B (n = 114)." (PMID 34437551, 2021). "Using multivariable logistic regression analysis of the RE HIP-transfused foals, the odds of pneumonia were approximately 6-fold higher (P = 0.0005) among foals with a low level of VapA antibody activity relative to foals with a high level of VapA antibody activity, accounting for effects of farm." (PMID 34437551, 2021). "The proportion of foals that developed pneumonia among foals with a low level of VapA activity was 40% (24/60), whereas the proportion of foals that developed pneumonia among foals with a high level of VapA activity was 18% (10/57)." (PMID 34437551, 2021). "Using multivariable logistic regression, the odds of pneumonia among foals transfused with RE HIP were approximately 7-fold higher (P = 0.0002) for foals at Farm A than for Farm B, accounting for effects of VapA antibody activity." (PMID 34437551, 2021).
viral infection (4 papers, 2022 to 2024). "Neither Prominin-1 (CD133) nor vesicle-associated membrane protein-associated protein A (VAPA) has been found to have a role in viral infection, including SARS-CoV-2 infection." (PMID 36152751, 2022). "Many of them, such as WDR7, INPP5E, CDK13, VAPA, NAMPT and PUM2, are known to be involved in viral infection mechanisms, whether at the point of the viral entry into the cell or during viral replication." (PMID 35563619, 2022).
amyotrophic lateral sclerosis (3 papers, 2020 to 2024). Amyotrophic lateral sclerosis (ALS) is a neurodegenerative disease characterized by progressive muscular paralysis reflecting degeneration of motor neurons in the primary motor cortex, corticospinal tracts, brainstem and spinal cord. "VAPA and VAPB are vesicle-associated membrane proteins that are associated with axonal transport of mitochondria and in the case of VAPB implicated in the pathology of amyotrophic lateral sclerosis (ALS8)." (PMID 33137126, 2020).
breast carcinoma (3 papers, 2007 to 2022). "Our analysis identified significant differential expression patterns for almost all our identified candidate biomarkers (except for VAPA), assessed using One-way ANOVA, among all 3 luminal-like breast cancers." (PMID 35971177, 2022).
colorectal cancer (2 papers, 2022 to 2026). A primary or metastatic malignant neoplasm that affects the colon or rectum. "Another study reported that the overexpression of miR-101-3p could reverse the pro-tumorigenic effect of cyclic RNA VAPA, which promoted colorectal cancer development." (PMID 35482720, 2022).
hepatocellular carcinoma (2 papers, 2019 to 2022). A malignant tumor that arises from hepatocytes. "Hepatocellular carcinoma (HCC)‐derived VAMP‐associated protein A (VAPA)‐enriched large oncosomes (LOs) facilitate bone metastasis (BM) via engineering an osteoclastic pre‐metastatic niche." (PMID 36169100, 2022). "Fusion transcripts of VAPA-Rab31 have been detected in lung adenocarcinoma and hepatocellular carcinoma (TCGA-LIHC/TCGA-ZP-A9D0)." (PMID 31083279, 2019). "Moreover, an in vivo experimental model using murine Hepa1‐6 hepatoma cell line and immunocompetent BALB/c mice was established to further examine the effect of VAPA‐enriched LOs on pre‐metastatic niche formation and bone metastasis." (PMID 36169100, 2022).
lung carcinoma (2 papers, 2019 to 2022). "Our data suggest that the fusion gene VAPA-Rab31 is a potential oncogene of lung cancer." (PMID 31083279, 2019). "Our data suggest the oncogenic function of the novel fusion gene VAPA-Rab31 via upregulated Bcl-2 and activated CREB in lung cancer." (PMID 31083279, 2019).
prostate carcinoma (2 papers, 2023 to 2024). A carcinoma that arises from epithelial cells of the prostate gland. "In summary, our study demonstrated that circTP63 promotes prostate cancer progression via directly binding to miR-421, thus increasing the expression of VAPA." (PMID 39247600, 2024). "The goal of this study was to investigate the role of circTP63/miR-421/VAPA axis in prostate cancer." (PMID 39247600, 2024). "Furthermore, the expression of VAPA was negatively correlated with that of miR-421 in prostate cancer tissues, and it was positively correlated with that of circTP3 in prostate cancer tissues." (PMID 39247600, 2024). "Also, tissue verification showed that VAPA was downregulated in prostate cancer tissues." (PMID 39247600, 2024). "Moreover, we examined the expression of VAPA in prostate cancer tissues." (PMID 39247600, 2024). "The results demonstrated that VAPA was upregulated in prostate cancer tissues compared with normal tissues." (PMID 39247600, 2024).
abscess (1 paper, 2023). An inflammatory process characterized by the accumulation of pus within a newly formed tissue cavity which is the result of a bacterial, fungal, or parasitic infection or the presence of a foreign body. "In goat case No. 2, the intramedullary cavity contained an abscess surrounded by radially arranged perpendicular spicules of new periosteal bone in the fifth right rib, and immunostaining with the anti-VapA monoclonal antibody 10G5 was negative." (PMID 37800907, 2023).
bacteremia (1 paper, 2018). "Of the 9 vapA-positive isolates, 6 came from patients in Texas, 2 in Minnesota, and 1 in Delaware; the only instance of vapA among the isolates with culture site information was in an HIV-positive bacteremia patient." (PMID 29300774, 2018).
lung adenocarcinoma (1 paper, 2019). A carcinoma that arises from the lung and is characterized by the presence of malignant glandular epithelial cells. "Here, we describe the identification of a fusion gene comprising part of the coding regions of Rab31 and VAMP-associated protein A (VAPA) through RNA-sequencing in patients with lung adenocarcinoma." (PMID 31083279, 2019). "A fusion transcript of Rab31 and VAPA was detected from RNA-sequencing data of a Korean patient with lung adenocarcinoma." (PMID 31083279, 2019). "In conclusion, we suggest that VAPA-Rab31 might be a novel oncogenic fusion gene that can be occurred upon genetic rearrangement in lung adenocarcinoma." (PMID 31083279, 2019).
metastasis (1 paper, 2022). The spread or migration of cancer cells from one part of the body (where they first appeared) to another. "Considering that bone metastasis is a common complication for many types of cancer, further investigation of whether the serum VAPA level correlates with BM from other cancer is warranted." (PMID 36169100, 2022).
neuritis (1 paper, 2012). A neuropathy arising from inflammation of one or more nerves. "Also, genes involved in nervous system development were found, for example ATP1B1 (involved in aggregation of neurons), TRIM2 (neuroprotection of cortical neurons) and VAPA, SGK1 and ZFYVE27 (involved in morphogenesis of neuritis)." (PMID 23028713, 2012).
osteosarcoma (1 paper, 2022). A usually aggressive malignant bone-forming mesenchymal neoplasm, predominantly affecting adolescents and young adults. "When expressed in human osteosarcoma U2OS cells, both EqtSMSS and EqtSolSS showed a reticular distribution that overlapped extensively with the ER marker protein VAPA." (PMID 36102623, 2022).
trisomy 18 (1 paper, 2010). Trisomy 18 is a chromosomal abnormality associated with the presence of an extra chromosome 18 and characterized by growth delay, dolichocephaly, a characteristic facies, limb anomalies and visceral malformations. "The ratios of methylated VAPA-APCDD1(chr18) to ZFY(chrY) were higher in maternal plasma samples of 9 male trisomy 18 fetuses than those of 27 male euploid fetuses (Mann-Whitney test, P = 0.029)." (PMID 21152411, 2010). "Digital PCR assays for VAPA-APCDD1 and ZFY DNA were performed on HinP1I- and HpaII-digested DNA samples extracted from placental tissues of five trisomy 18 and five euploid male fetuses." (PMID 21152411, 2010).
infection (14 papers, 2010 to 2025). The state of being infected such as from the introduction of a foreign agent such as serum, vaccine, antigenic substance or organism. "Following infection of bone marrow-derived macrophages with L. amazonensis metacyclic promastigotes, we observed that VAPA gradually associates with communal parasitophorous vacuoles." (PMID 40163521, 2025). "VAPA performs important functions during infection as both microbes and antimicrobial host molecules target VAPA and its client proteins." (PMID 28698274, 2017). "AcrV and VapA antigens from Aeromonas salmonicida affecting salmon were stably expressed in chloroplasts of Chlamydomonas reinhardtii, showing elevated immune production during infection." (PMID 39335281, 2024). "Therefore, the results of this assay suggest that CD133, CDH17, and VAPA partially contribute to infection in ACE2-expressing cells." (PMID 36152751, 2022). "Whether PA really is a central binding partner of VapA during an infection remains to be shown." (PMID 36786596, 2023). "Remarkable differences in virulence between vapA-absent and vapA+ isolates became evident in the intraperitoneal challenge model of infection." (PMID 40093535, 2025). "Additionally, infection of OSBP-depleted, or VAPA/B double knockout cells resulted in increased cytoplasmic S. Typhimurium, suggesting a stabilization role of OSBP and VAPA/B for the SCV." (PMID 37223745, 2023). "Consistent with this, we recently showed that later in infection, RCV displaying VapA at the membrane and containing replicating R. equi were lacking lysosomal membrane protein 1 (LAMP-1), whereas RCV without VapA at the membrane were LAMP-1 positive and contained fewer bacteria." (PMID 30286098, 2018). "In addition, parallel infection of cells expressing neither VAPA nor VAPB showed no titer reduction, indicating that the minor decrease is most likely not due to the VAPB deficiency." (PMID 34200728, 2021). "In the infection assays using cells expressing each candidate molecule alone, almost no infection was observed, which indicated that CD133, CDH17, and VAPA were not the primary receptors for the SARS-CoV-2 spike protein." (PMID 36152751, 2022). "Eight days after infection with R. equi, BALB/c mice showed bacterial burden in the lung, liver, and spleen, which was significantly diminished in the animals that were immunized with live attenuated Salmonella expressing the VapA protein; i.e., with χ3987-pYA3137vapA (data not shown)." (PMID 20072623, 2010).
cancer (9 papers, 2007 to 2022). A tumor composed of atypical neoplastic, often pleomorphic cells that invade other tissues. "However, further functional analysis is necessary to understand the molecular mechanisms of VAPA-Rab31-directed cancer progression." (PMID 31083279, 2019). "However, cells expressing VAPA-Rab31 might be selected and expanded during cancer progression because of a growth and/or survival advantage." (PMID 31083279, 2019). "Multiple candidates for PTEN ceRNAs by bioinformatics prediction including PTEN pseudogene transcript PTENP1, VAPA, CONT6L, and so on, have been validated experimentally in human cancers." (PMID 27486764, 2016). "The VAPA gene, which was overexpressed in most of the cancer samples but not in CUP or LAC, revealed a striking contrast between CUP/LAC and other samples, which may have influenced the clustering analysis." (PMID 23671674, 2013).
tumor (9 papers, 2016 to 2026). "Notably, tumor formation in the xenograft mice injected with VAPA-Rab31-overexpressing cells was also associated with metastasis formation in lungs and liver." (PMID 31083279, 2019). "CONCLUSION: Endothelial cell-derived IGFBP7 suppresses CRC progression via the EGR1/TGF-β1 pathway, while VAPA-mediated lysosomal degradation limits its tumor-suppressive function." (PMID 41692778, 2026). "Tumor growth was dramatically increased in mice that were injected with the VAPA-Rab31-overexpressing cells." (PMID 31083279, 2019). "For instance, it has been shown that the expression of the tumor-suppressor gene PTEN can be regulated by its miRNA-mediated competitors VAPA, CNOT6L, SERINC1 or ZNF460." (PMID 26812364, 2016). "Notably, we identified Vesicle-associated membrane protein-associated protein A (VAPA) as a key mediator in the transport of IGFBP7 vesicles to lysosomes, facilitating IGFBP7 degradation and thereby attenuating its tumor-suppressive function." (PMID 41692778, 2026). "Furthermore, we examined the effects of VAPA-Rab31 fusion on tumor growth in vivo using mouse xenograft model in which VAPA-Rab31-overexpressing Beas-2B cells were injected subcutaneously." (PMID 31083279, 2019). "Tumor methylation data were used to build a methylation signature of PTEN loss in our cohort, which was confirmed in TCGA, and included CpGs in ATP11A, GDNF, JAK1, JAM3, and VAPA." (PMID 29137428, 2017). "A further two-group analysis between NIBUC and MIBUC also demonstrated the overexpression of DEPs with a tumor-suppressive role, including LGALS3 and VAPA in NIBUC." (PMID 32326232, 2020). "VAPA-Rab31 fusion was highly expressed only in the tumor of the patient, and not in the matched normal tissue as confirmed by RT-PCR." (PMID 31083279, 2019). "We observed VAPA-Rab31 overexpression in the tumor tissue from a patient and not in the paired normal tissue." (PMID 31083279, 2019). "However, it is worth noting that circVAPA may also mediate CRC by regulating the expression of VAPA, among them, the VAPA can act as a ceRNA to regulate phosphatase and tensin homolog (PTEN) to play a tumor suppressor effect." (PMID 34796685, 2021).
VAPA also shares sentences with these, for which no sentence is quoted: colon carcinoma (3 papers); amyotrophic lateral sclerosis type 8 (1); Autoimmunity (1); bladder cancer (1); cystinosis (1); dyslipidemia (1); fragile X syndrome (1); Granuloma (1); HCMV infection (1); HIV-1 infection (1); malaria (1); melanoma (1); motor neuron disease (1); neurodegenerative disease (1); neurological disorders (1); pancreatic cancer (1); Phelan-McDermid syndrome (1); respiratory infection (1); spinal muscular atrophy (1); thyroid disease (1).